PGCKA1 (PDCD10 and GCKIII kinases associated 1)
Description:
Acts as a tumor suppressor. Acts as a tumor suppressor for colorectal cancer cell proliferation by targeting KEAP1/USP17/ELK1/CDK6 axis.
Synonyms: C4orf19; FLJ11017
Tractability: Antibody: UniProt places it where antibodies can reach, with high confidence; its Gene Ontology location is reachable by antibodies, with medium confidence.
Gene: Protein-coding gene on chromosome 4 (37,453,439 to 37,624,344, forward strand). Ensembl gene ENSG00000154274.
Subcellular location: Cell membrane
Subcellular location (Human Protein Atlas): Nucleoplasm; Cell Junctions
Gene Ontology:
Molecular function: protein binding
Biological process: regulation of cell cycle
Cellular component: cell periphery; plasma membrane
Genetic constraint (gnomAD): Loss-of-function variants: 1 observed, 2.35 expected, observed/expected ratio (o/e) 0.43, 90% interval 0.15 to 1.66. That is too few expected variants to judge how well the gene tolerates losing a copy. Missense variants: 327 observed, 391.43 expected, observed/expected ratio (o/e) 0.84, 90% interval 0.76 to 0.92. Synonymous variants: 117 observed, 150.69 expected, observed/expected ratio (o/e) 0.78, 90% interval 0.67 to 0.9.
Homologues: Orthologues: chimpanzee C4H4orf19 (99% identical), macaque C5H4orf19 (90% identical), pig PGCKA1 (61% identical), rabbit PGCKA1 (60% identical), mouse Pgcka1 (57% identical), guinea pig PGCKA1 (57% identical), rat C14h4orf19 (56% identical), dog C3H4orf19 (34% identical).
Diseases named in the same sentence as PGCKA1 in open-access papers:
PGCKA1 is named in the same sentence as 13 diseases in open-access papers, as found by Europe PMC text mining. Sharing a sentence is not in itself a finding about the gene and the disease.
PGCKA1 shares sentences with these, for which no sentence is quoted: tumor (4 papers); cancer (3); colon adenocarcinoma (2); colorectal cancer (2); Anxiety (1); breast carcinoma (1); breast lobular carcinoma (1); clear cell renal carcinoma (1); head and neck squamous cell carcinoma (1); lymph node metastases (1); pancreatic cancer (1); renal carcinoma (1); urinary bladder transitional cell papilloma (1).